PMS2P2 (PMS1 homolog 2, mismatch repair system component pseudogene 2)
Synonyms: PMS4; formerly PMS2L2
Gene: Transcribed unprocessed pseudogene on chromosome 7 (75,344,015 to 75,359,550, reverse strand). Ensembl gene ENSG00000278416.
Diseases named in the same sentence as PMS2P2 in open-access papers:
PMS2P2 is named in the same sentence as 1 disease in open-access papers, as found by Europe PMC text mining. Sharing a sentence is not in itself a finding about the gene and the disease.
PMS2P2 shares sentences with these, for which no sentence is quoted: osteoarthritis (1 paper).